SNHG1 (small nucleolar RNA host gene 1)
Diseases named in the same sentence as SNHG1 in open-access papers (continued):
Sharing a sentence is not in itself a finding about the gene and the disease.
bladder cancer (22 papers, 2020 to 2025). "Secondly, we found that the stemness and the invasiveness of bladder cancer cells induced by SNHG1 over-expression are closely linked and are both driven by the over-expression of Rac1." (PMID 36077697, 2022). "Moreover, we investigated the underlying mechanism of SNHG1 in the bladder cancer process via miR-9-3p/MDM2/PPARγ axis." (PMID 36230661, 2022). "Therefore, high SNHG1 expression was associated with poor prognosis of patients with bladder cancer." (PMID 36230661, 2022). "For example, in bladder cancer, lncRNAs such as TUG1 and SNHG1 have been implicated in modulating autophagy and contributing to therapy resistance through interactions with key signaling pathways like PI3K/Akt/mTOR and PP2A catalytic subunit, respectively." (PMID 39512820, 2024). "Similar trends were observed in The Cancer Genome Atlas (TCGA) database, which showed elevated SNHG1 expression in patients with bladder cancer when compared to normal bladder tissues." (PMID 38365726, 2024). "High small nucleolar RNA host gene 1 (SNHG1) expression is positively correlated with bladder cancer cell invasion, proliferation, and autophagy, and SNHG1 functions through the miR-493-5p/ATG14 pathway." (PMID 38481525, 2024). "We also investigated SNHG1 expression in normal human bladder urothelial cell (UROtsa) and various human bladder cancer cell lines such as J82, UMUC3, T24T, U5637." (PMID 38365726, 2024). "Studies have found that small nucleolar RNA host gene 1 (SNHG1) is a lncRNA that is regulated in the development of bladder cancer." (PMID 37489458, 2023). "In bladder cancer, SNHG1 promotes tumor cell proliferation and inhibits apoptosis by regulating PPARγ ubiquitination." (PMID 37686677, 2023). "SNHG1, therefore, is worthy of further evaluation as a new adjunct biomarker to predict the progression and prognosis of advanced bladder cancers." (PMID 36077697, 2022). "Initially, data from our project and online database unraveled that SNHG1 was highly expressed in bladder cancer tissues and cells." (PMID 36230661, 2022). "We carried out the present study to determine the functional significance of the preferential over-expression of SNHG1 in advanced human bladder cancers." (PMID 36077697, 2022). "Further investigations of our study identified that miR-9-3p inhibition led to increase of cell proliferation and decrease of apoptosis in vitro and promotion of tumorigenesis in vivo and reversed the effect of SNHG1 silencing in bladder cancer." (PMID 36230661, 2022). "It was validated that SNHG1 was overexpressed in bladder cancer tissues detected by qRT-PCR and FISH, which was also associated with poor clinical outcome." (PMID 36230661, 2022). "The expression of miR-9-3p was negatively correlated to the expression of SNHG1 in bladder cancer tissues." (PMID 36230661, 2022). "Analysis of TCGA database data by Ualcan revealed that DIO3OS was significantly underexpressed in bladder cancer (p = 1.949 × 10−5), while SNHG1 was significantly overexpressed in bladder cancer (p = 3.889 × 10−11)." (PMID 36230661, 2022). "Increased expression of SNHG1 has been shown to enhance bladder cancer progression and autophagy via miR-493-5p/ATG14/autophagy pathway." (PMID 36685879, 2022). "Conclusions: the study elucidated that SNHG1 played an important role in bladder cancer and provided a potential therapeutic target for bladder cancer." (PMID 36230661, 2022). "Through Rac1, SNHG1 also markedly stimulates the stem-cell-like sphere formation of bladder cancer cells." (PMID 36077697, 2022). "In summary, silencing SNHG1 decreased the tumorigenesis of bladder cancer cells in vivo by decreasing MDM2 expression through miR-9-3p." (PMID 36230661, 2022). "We screened for, pinpointed, and functionally validated specific signaling molecules and mechanisms of action of key components of the SNHG1 effector pathway that stimulated bladder cancer cell stemness and invasion." (PMID 36077697, 2022).
bladder cancer (continued). "To further examine the regulatory role of SNHG1 in bladder cancer, we selected one normal urothelial cell line SV-HUC-1 and four bladder cancer cell lines (5637, T24, SW780, and UM-UC-3)." (PMID 36230661, 2022). "Having demonstrated the effects of the SNHG1/DNMT3A/miR-129-2-5p/Rac1 effector pathway on promoting bladder cancer cell stemness and invasion, we investigated more directly the functional relationship between stemness and invasion." (PMID 36077697, 2022). "Specifically, we found that the increased Rac1 protein in bladder cancer cells over-expressing SNHG1 was due to the increased stability of Rac1 mRNA, and that this was associated with low levels of miR-129-5p." (PMID 36077697, 2022). "Conclusively, silencing SNHG1 bound to miR-9-3p can inhibit bladder cancer cell proliferation and tumorigenesis." (PMID 36230661, 2022). "RNA-FISH showed high SNHG1 expression in bladder cancer tissues compared with adjacent normal tissues as well." (PMID 36230661, 2022). "Firstly, we found a functional link between the over-expression of SNHG1 and the stem-cell-like behavior of bladder cancer cells." (PMID 36077697, 2022). "The study aimed to investigate the role and mechanism of lncRNA Small Nucleolar RNA Host Gene 1 (SNHG1) in Bladder Cancer (BC) progression." (PMID 36087568, 2022). "Here, we provide experimental evidence establishing that SNHG1 drives bladder cancer cell invasion and stem-cell-like behaviors through a specific signaling pathway." (PMID 36077697, 2022). "We examined how the enforced over-expression, and conversely the knockdown, of SNHG1 affected bladder cancer cell sphere formation, migration, and invasion." (PMID 36077697, 2022). "Further detection by qRT-PCR assay also found that SNHG1 was highly expressed in bladder cancer tissues." (PMID 36230661, 2022). "Collectively, this study provides evidence that SNHG1 upregulation promoted cell proliferation but depressed cell apoptosis in bladder cancer via MDM2-inhibited PPARγ by binding to miR-9-3p." (PMID 36230661, 2022). "To date, however, nothing is known about the role of Rac1 in bladder cancer stemness and invasion or about the functional relationship linking Rac1 with SNHG1." (PMID 36077697, 2022). "We found that the expression of SNHG1 was significantly up-regulated in bladder cancer after analyzing data obtained from TCGA and GEO." (PMID 36230661, 2022). "Nevertheless, the biological functions and potential mechanism of SNHG1 in bladder cancer (BC) are uncharacterized." (PMID 32885590, 2020). "Additionally, they found that SNHG1 enhances the proliferation of bladder cancer cells through the suppression of apoptosis and promotes MDM2 expression by binding to miR-9-3p, which in turn facilitates the ubiquitination and downregulation of PPARγ." (PMID 40771930, 2025). "They further demonstrated that SNHG1 promotes the proliferation of bladder cancer cells by inhibiting apoptosis, thereby corroborating their hypothesis that SNHG1 can inhibit apoptosis." (PMID 40771930, 2025). "SNHG1 was also found to interact with PP2A-c to promote bladder cancer invasion." (PMID 37464317, 2023). "This suggested that silencing SNHG1 could trigger the inhibition of cell proliferation and promotion of cell apoptosis in bladder cancer." (PMID 36230661, 2022). "RNA-FISH showed that SNHG1 was localized in the cytoplasm, suggesting that SNHG1 may be involved in the process of bladder cancer by affecting miR." (PMID 36230661, 2022). "In summary, SNHG1 overexpression promoted bladder cancer cell tumorigenesis in vivo." (PMID 36230661, 2022). "Overall, we believe that the identification of the SNHG1/DNMT3A/miR-129-2-5p/Rac1 effector pathway that plays a major role in driving bladder cancer stemness and invasion may help develop a new therapeutic approach to treat this difficult disease." (PMID 36077697, 2022). "It was found that only DIO3OS and SNHG1 were significantly differential lncRNAs in bladder cancer." (PMID 36230661, 2022).
bladder cancer (continued). "Furthermore, increased SNHG1 expression enhances bladder cancer cell proliferation, invasion, and autophagy via the miR-493-5p/ATG14/autophagy pathway." (PMID 35669241, 2022). "Another study reveals the role of SNHG1 in bladder cancer progression via regulating EZH2." (PMID 35236381, 2022). "Here, we show that SNHG1, a long non-coding RNA that is over-expressed in ~95% of human muscle-invasive bladder cancers (MIBCs), induces stem-cell-like sphere formation and the invasion of cultured bladder cancer cells by upregulating Rho GTPase, Rac1." (PMID 36077697, 2022). "Additionally, when SNHG1 was silenced in bladder cancer cells and mice, cell proliferative capacity was depressed but cell apoptosis was accelerated in vitro, and tumorigenesis was inhibited in vivo." (PMID 36230661, 2022). "Then, we explored the downstream miR of SNHG1 in bladder cancer." (PMID 36230661, 2022). "Taken these findings into account, we hypothesized that the SNHG1/miR-9-3p/MDM2/PPARγ axis correlated to the progression of bladder cancer." (PMID 36230661, 2022). "Consequently, this research investigated the mechanism of SNHG1 in bladder cancer with the involvement of miR-9-3p." (PMID 36230661, 2022). "Hence, these results confirmed that SNHG1 overexpression promoted bladder cancer progression by binding to miR-9-3p." (PMID 36230661, 2022). "Because SNHG1 is over-expressed in ~95% of human muscle-invasive bladder cancers, it may serve as a useful predictive marker for bladder cancer invasion and progression." (PMID 36077697, 2022). "Moreover, it has been shown that long noncoding RNA SNHG1 activates autophagy and promotes cell invasion in bladder cancer." (PMID 35846147, 2022). "•lncRNA SNHG1 played an oncogenic role in bladder cancer, indicating poor prognosis." (PMID 36087568, 2022). "Therefore, the present study was implemented by focusing on the alteration in SNHG1 expression and function in bladder cancer." (PMID 36230661, 2022). "Collectively, SNHG1 upregulation promoted the proliferation of bladder cancer cells." (PMID 36230661, 2022). "Simultaneously, in vivo experiments showed that the tumorigenic ability of bladder cancer cells in vivo was diminished by treatment with sh-SNHG1 alone and elevated by treatment with miR-9-3p inhibitor alone, which was neutralized by co-treatment with sh-SNHG1 and miR-9-3p antagomir." (PMID 36230661, 2022). "It was recently reported that lncRNA small nucleolar RNA host gene 1 (SNHG1) is expressed in several cancer types such as breast, colorectal, pancreatic and neuroblastoma as a competitive endogenous RNA and can inhibit PPARγ expression to promote bladder cancer pathogenesis." (PMID 39199690, 2024). "Additionally, as stemness is a major contributor to tumor heterogeneity, SNHG1 could be a key epigenetic regulator influencing the diverse molecular subtypes that have recently been described in bladder cancer." (PMID 36077697, 2022). "However, the potential role of SNHG1 remains to be investigated in bladder cancer." (PMID 36230661, 2022). "The lncRNA SNHG1 is able to interact with catalytic subunit PP2A and stimulate autophagy to enhance metastasis of bladder cancer." (PMID 39512820, 2024). "We found that SNHG1 was significantly up-regulated in human bladder cancer tissues, and PTEN protein level was significantly downregulated in advanced bladder cancer tissues, which supported our conclusion." (PMID 38365726, 2024). "SNHG1 has also been shown to interact with the RNA-binding matrix protein, matrin-3 (MATR3) in neuroblastoma, and PP2A-c in bladder cancer." (PMID 37464317, 2023). "To determine the functional significance of SNHG1, which is frequently over-expressed in human MIBC specimens, we stably transfected cultured T24T bladder cancer cells with a SNHG1-bearing plasmid." (PMID 36077697, 2022).
bladder cancer (continued). "Our data strongly suggest that the SNHG1/DNMT3A/miR-129-2-5p/Rac1 effector pathway drives stem-cell-like and invasive behaviors in MIBC, a deadly form of bladder cancer." (PMID 36077697, 2022). "Additionally, in bladder cancer, lncRNAs like TUG1 and SNHG1 have been shown to modulate autophagy through interactions with signaling pathways such as miR-145/ZEB2 and PP2A catalytic subunit, respectively." (PMID 39512820, 2024). "Moreover, SNHG1 enhances HK2 expression by competitively regulating miR-143-3p expression, thus promoting bladder cancer cell proliferation." (PMID 38706912, 2024). "In this way, SNHG1 enhances EZH2 expression in the nucleus to down-regulate CDH1, resulting in a decrease in E-cadherin levels and promoting metastasis and migration of bladder cancer cells." (PMID 35236381, 2022). "By defining a functional signaling pathway, i.e., SNHG1/DNMT3A/miR-129-2-5p/Rac1, that drives stemness and invasion in advanced bladder cancer cells, our study should spur additional investigation into the value of therapeutically targeting components of this pathway." (PMID 36077697, 2022). "Altogether, we clearly show that SNHG1 over-expression inhibits miR-129-5p expression, thereby reducing the ability of the latter to bind to the 3′-UTR Rac1 mRNA and increasing the stability of Rac1 mRNA and promoting bladder cancer cell stemness and invasion." (PMID 36077697, 2022). "Notably, the present study provided evidence that SNHG1 promotes MDM2 expression by binding to miR-9-3p to promote PPARγ ubiquitination and downregulate PPARγ expression, thereby resulting in elevation of bladder cancer cell proliferation in vitro and tumorigenesis in vivo." (PMID 36230661, 2022). "Our study elucidated that SNHG1 promotes MDM2 expression by binding to miR-9-3p to promote PPARγ ubiquitination and downregulate PPARγ expression and that SNHG1 plays an important role in bladder cancer and provides a potential therapeutic target for bladder cancer." (PMID 36230661, 2022). "By identifying the DNMT3A/miR-129-2-5p/Rac1 signaling pathway downstream of SNHG1 that is operative in advanced bladder cancer cells, we are in no way ruling out other potential pathways or components that might also mediate the activities of SNHG1." (PMID 36077697, 2022).
gastric cancer (22 papers, 2015 to 2025). A primary or metastatic malignant neoplasm involving the stomach. "Among them, SNHG1 has been previously implicated in tumor proliferation and metastasis, particularly in esophageal squamous cell carcinoma and gastric cancer, where it exerts oncogenic effects through pathways such as PI3 K/AKT or Wnt/β-catenin." (PMID 40629071, 2025). "Additionally, previous studies have shown that the differential expression of lncRNA SNHG1 is upregulated in gastric cancer, indicating that it is associated with the development of gastric cancer." (PMID 32423385, 2020). "Among the up-regulated dp-lncRNAs, SNHG1 has been implicated in cellular proliferation and migration and invasion of different cancer types, and to be strongly up-regulated in osteosarcoma, nonsmall lung cancer, and gastric cancer." (PMID 32079618, 2020). "Gastric cancer is the third leading cause of death worldwide. in colon cancer tissues, the patients also showed the short life time when the expression of SNHG1 was significantly high." (PMID 31691514, 2019). "SNHG1 up-regulates in colorectal, liver, prostate and gastric cancers, which is the biomarker for decreased survivals." (PMID 34336652, 2021). "Based on this background, we supposed that lncRNA SNHG1 promotes EMT in gastric cancer cells via the miR-15b-regulated DCLK1/Notch1 axis." (PMID 32423385, 2020). "Liu ZQ and others discovered the mechanism of SNHG1 in promoting EMT in gastric cancer cells." (PMID 35310912, 2022). "Consistent with this, SNHG1 is upregulated in gastric cancer." (PMID 26061048, 2015). "Similarly, SNHG1 has been shown as a contributor to gastric cancer proliferation through DNMT1." (PMID 34712495, 2021). "Some lncRNAs affect the glycolysis process by regulating the expression of key enzymes of glycolysis and inducing drug resistance in gastric cancer cell lines; these include, for instance, SNHG7, HAGLR, and SNHG1." (PMID 38927012, 2024).
non-small cell lung carcinoma (22 papers, 2017 to 2024). A group of at least three distinct histological types of lung cancer, including non-small cell squamous cell carcinoma, adenocarcinoma, and large cell carcinoma. "SNHG1 promotes non-small cell lung cancer tumorigenesis and progression via the miR-101-3p/SOX9/Wnt/β-Catenin axis." (PMID 39519092, 2024). "A limited study of non-small cell lung cancer showed that SNHG1 knockdown resulted in reduced proliferation." (PMID 37464317, 2023). "For instance, SNHG1 promotes non-small cell lung cancer progression through inhibiting miR-101-3p expression and activating the Wnt/β-catenin signaling pathway." (PMID 32497022, 2020). "A recently described lncRNA involved in TGFβ-mediated EMT in non-small cell lung cancer (NSCLC) is the small nucleolar RNA host gene 1 lncRNA (lnc-SNHG1)." (PMID 31003545, 2019). "Upregulated lncRNA SNHG1 contributes to the progression of non-small cell lung cancer through activation of the Wnt/β-catenin signaling pathway." (PMID 29340250, 2018). "In the current study, we found that expression of SNHG1 was up-regulated in non-small cell lung cancer (NSCLC) tissues and cell lines." (PMID 28147312, 2017). "Meanwhile, lncRNA SNHG1 is upregulated and contributes to progression of non-small cell lung cancer through inhibition of miR-101-3p and activation of Wnt/β-catenin signaling pathway." (PMID 29340086, 2017). "In limited studies in non-small cell lung cancer, SNHG1 knockdown reduced proliferation." (PMID 37464317, 2023). "SNHG1 has been reported to up-regulated MTDH by sponging miR-145-5p and led to non-small cell lung cancer progression." (PMID 38635069, 2024). "Besides, SNHG1 accelerates the deterioration of non-small cell lung carcinoma (NSCLC) by negative modulation of miR-497." (PMID 31615767, 2019).